IL1B (interleukin 1 beta)
Diseases named in the same sentence as IL1B in open-access papers (continued):
Sharing a sentence is not in itself a finding about the gene and the disease.
tumor (continued). "In contrast to monocytes, macrophages and endothelial cells from tumors of Il1b-/- mice showed comparable JAM-A expression to wild-type controls, indicating that expression of JAM-A in these cells was not modulated by IL1β within the tumor microenvironment." (PMID 36531986, 2022). "Although caspase-8 was activated in tumor-infiltrating myeloid cells, its deletion was not sufficient to completely block bioactive IL-1β release and neutrophil infiltration." (PMID 35517498, 2022). "However, IL-1β also creates a tumor immunosuppressive microenvironment predominantly by TAM and MDSC, which promotes tumor development." (PMID 35739593, 2022). "Moreover, an elevated expression of IL1β was detected in RCC patients’ plasma and circulating monocytes; higher levels of this cytokine inside the tumor correlated with advanced tumor stage as well as with macrophage infiltration." (PMID 35814450, 2022). "Activating TLR4 may recede the suppressive inflammatory factors expression, including NF-κB, IL-1β, and IL-18 by the ASCL2 regulation, and induce the inflammatory injury to tumor cells, thereby being involved in the prognosis of this disease." (PMID 36008864, 2022). "Interestingly, we have previously showed an increase in both IL1B and IL8 gene expression in AA tumor samples, increased presence of myeloid cells, as well as upregulation of genes related to myeloid-derived suppressor cells." (PMID 36531053, 2022). "NLRP3 mediates anti-tumor immunity in CRC via two key cytokines, IL18 and IL1β." (PMID 36077828, 2022). "Our findings support the critical role of efferocytosis of tumor AC to activate NLRP3-dependent inflammasome signaling in the TME to induce non-pyroptotic IL-1β secretion which subsequently promotes tumor growth (Graphical Abstract)." (PMID 36439171, 2022). "However, when ATO was added to the THP-1–tumor cell coculture system, ICAM1 induction was attenuated in HNSCC cells, suggesting that ATO modulates IL-1β secretion by modulating macrophage function." (PMID 36264639, 2022). "Moreover, IL-1β activates the NF-kB signaling pathway of myeloid-derived suppressor cells (MDSCs), which increases IL-6 and TNF-α secretion, enhancing tumor growth." (PMID 35892729, 2022). "After therapeutic period, Andro could remarkably reduce IL-6, IL-1β, TNF-α, VEGF, MMP-2 level in blood and IL-10, TGF-β, NF-κB level of tumor tissue with significantly statistical implications (p < 0.01)." (PMID 33967748, 2021). "We suggested that inhibition of IL-1B using Canakinumab supports an epithelial rather than a mesenchymal phenotype thus, favoring tumour proliferation while inhibiting EMT and therefore metastasis." (PMID 34290237, 2021). "The secretion profile of some of the cytokines related to inflammation in addition to tumor invasion, progression, and migration, namely, IFN-γ, TNF-α, IL-1β, IL-6, IL-8, and IL-12, demonstrated a decrease in values following treatment with the hWJSC-CC, hWJSC-CM (100%), and hWJSC-L (15 μg/ml)." (PMID 33869169, 2021). "The blockade of TNFα and IL1β with adalimumab and anti-IL1β antibody respectively, as well as the application of focal adhesion kinase (FAK) inhibitor, effectively ameliorated endothelial activation induced by CAR-T, tumor cells, and myeloid cells." (PMID 34093519, 2021). "In addition, the inhibition of FAK, the critical kinase mediating both TNFα and IL1β signaling, effectively ameliorated endothelial dysfunction induced by CAR-T/tumor cells/myeloid cells." (PMID 34093519, 2021). "To establish the role of TXNIP and downstream genes HIF1α and IL1β in the biology of cRCC, we have applied immunohistochemistry to tissue multi-arrays containing tumours of patients without detectable metastases at the time of operation." (PMID 34433833, 2021). "Moreover, adalimumab and anti-IL1β antibody exerted synergistic effect on the prevention of endothelial activation induced by CAR-T, tumor cells, and myeloid cells." (PMID 34093519, 2021).
tumor (continued). "As a monotherapy, CD8α ALN-1 showed a modest effect on tumor growth, which was absent in mice that received WT IL-1β or untargeted BcII10 ALN-1." (PMID 34772757, 2021). "Furthermore, LyeTx I-b seems to be an efficient regulator of the 4T1 tumor microenvironment by modulating several cytokines, such as TGF-β, TNF-α, IL-1β, IL-6, and IL-10, in primary tumor and lung, spleen, and brain." (PMID 34572719, 2021). "Furthermore, TMR with a glycolytic preference instills a “domino effect” by mediating the aggregation of various glycolytic and chemoresistance activators (VEGF, IL-1β, IL-8, IL-6, TGF-β, and lactate) within the tumor stroma." (PMID 34831136, 2021). "Thus, on one hand, pro-inflammatory cytokines released by tumor-infiltrating immune cells, such as TNF-α and IL-1β, can favor recruitment and activation of mesenchymal progenitor cells into tumors." (PMID 34663337, 2021). "Confirming TBK1 vs. IKKα/β dichotomy of mRIPO vs. LPS treatment, tumor homogenate cytokine analysis revealed stronger IKKα/β-driven cytokine induction by LPS (IL-6, TNF, IL-1β, IL-10), with CXCL10 (TBK1-dependent) being the most prominently induced cytokine after mRIPO treatment." (PMID 33767151, 2021). "In addition, IL-1β induces the expression of CCL2 in TAMs and tumor cells, leading to the recruitment of myeloid cells such as myeloid derived suppressor cells (MDSCs) and TAMs into the TME." (PMID 34625124, 2021). "In addition, TAMs play an important role in tumor neovascularization by secreting proangiogenic factors, such as VEGF, TNF, IL-1β, IL-8, PDGF, FGF, and others." (PMID 33916915, 2021). "The secreted IL-1β into the TME promotes tumorigenesis, tumor invasiveness and immunosuppression." (PMID 34379689, 2021). "We silenced IL1β in tumor cells to demonstrate that such cells do not exert an influence on NCFs inflammatory phenotype." (PMID 34066976, 2021). "Such biochemical and cellular alterations may in turn result in an inflammatory local response potentially mediated by IL-6, IL-1β, and TNF-α, and inhibition of tumor growth." (PMID 34060472, 2021). "Interestingly, preclinical RCC data have demonstrated that inhibitors to CXCR2, IL-1β, class I histone deacetylase (HDAC), and HMGB1 can slow tumor growth and potentially synergize with anti-PD-1 blockade in an MDSC inhibition-dependent manner." (PMID 34831452, 2021). "A pro-inflammatory environment (IL1β and TNF) could stimulate tumor growth but also promote tumoricidal M1 macrophage activity." (PMID 34209203, 2021). "We first asked whether LNCaP and PC3 cell lines, characterized by different androgen responsiveness and thus modelling different tumor progression stages, may have a different inflammatory profile regarding NLRP3-inflammasome activation and IL-1β maturation." (PMID 34070682, 2021). "Interestingly, the effect of CBM-dependent NF-κB activation is not only confined to tumour growth but also extends to affect the tumour’s microenvironment by stimulating the secretion of VEGF, interleukin-6 (IL-6), IL-8, and IL-1B." (PMID 34539580, 2021). "Interestingly, the levels of the NLRP3 complex components (NLRP3, ASC and IL-1β) were significantly elevated in oral cavity squamous cell carcinoma (OSCC) and contributed to tumor growth and metastasis." (PMID 34064909, 2021). "We observed significant negative correlations between CD68+ macrophage infiltrations in the tumor tissue and the concentrations of the cytokines eotaxin, IFN-γ, IL-1β, IL-2, IL-10, IL-13, IL-16, VEGF and factor score of component 2 (“Inflammatory Cluster”) in the CSF." (PMID 34654395, 2021). "Consistently with the increased proportion of MDMs expressing M1 markers, we observed that the co-culture of murlentamab-opsonized SKOV3-R2+ tumor cells with both M0 and TAM-like MDMs induced a significant increase in IL1β, IL6 and IFNγ pro-inflammatory cytokine production." (PMID 33924378, 2021).
tumor (continued). "Additionally, subjects with the lowest survival probability expressed very few immune-related genes at high levels, many of which are known to promote tumor progression, including IL1A, IL1B, and TGFB, and which were also correlated with increased FIGO stage." (PMID 33834038, 2021). "Bone marrow and spleen cells derived from tumor-bearing mice spontaneously released higher levels of IL-1β and IL-6 during 48 h in culture, compared to nontumor-bearing mice." (PMID 33649199, 2021). "In addition, IL-1β acts as an amplifier of immune reactions inducing MCP-1 expression in monocytes, regulating myeloid cell recruitment into tumor tissue, and leading to inflammation." (PMID 33435371, 2021). "The absence of IL-1 signaling in IL-1β K/O mice promoted regulatory T cell development that suppressed anti-tumor immunity." (PMID 33686176, 2021). "M2-like macrophages have been reported to upregulate the expression of the glucose-regulated protein of 78 kDa (GRP78) in tumor cells, promoting STAT3 phosphorylation, leading to the downstream inflammatory factors including IL-1β and TNF-α upregulation, which facilitates tumor progression." (PMID 34326840, 2021). "In addition, a variety of tumor-originated cytokines, such as G-CSF, VEGF, IL-6, and IL-1β, have been proven to promote MDSCs accumulation." (PMID 34899747, 2021). "Other cytokines (CCL2, IFNγ, IL-12, IL-10, TNFα, IL-4, and IL-1β) evaluated were not significantly changed, suggesting that additional unidentified tumor-derived soluble factors promote alternative activation in BMDMs." (PMID 35008514, 2021). "TGFB1, IL1B, IL10, IL6, PTGS2, and PPARG closely interacted with the tumor microenvironment." (PMID 34394377, 2021). "When compared with tumor specimens from mice bearing colony not secreting IL-1β, MDA-MB-231 xenografts harvested from mice bearing colony secreting IL-1β exhibited a higher protein expression of HIF-1α." (PMID 34571989, 2021). "To establish the role of TXNIP and downstream genes HIF1α and IL1β in the biology of cRCC, we have applied immunohistochemistry to multi-tissue arrays containing tumours of 691 patients without detectable metastases at the time of operation." (PMID 34433833, 2021). "Using syngeneic IL-1B/IL1R1 knock out mouse models in combination with genetic manipulation of tumour cells to overexpress IL-1B/IL1R1, we found that IL-1B signalling elicited an opposite response in primary tumours compared with bone metastases." (PMID 34290237, 2021). "Our data showed that lack of IL-1B resulted in increased primary tumour growth and decreased infiltration of MPO+ neutrophils and F4/80+ macrophages." (PMID 34290237, 2021). "Furthermore, IL-6, IL-1β, VEGF, GM-CSF, and G-CSF can contribute to MDSC infiltration in the tumor microenvironment." (PMID 34947886, 2021). "Besides, administration of Salmonella also recruits macrophages into tumor tissue, which then secrete TNF-α and IL-1β for exerting anticancer effects." (PMID 33717106, 2021). "As tumor spheroids are formed primarily by cancer stem cells (CSCs) and require the formation of cell-to-cell contacts, we next determined the stemness of TNBC cells that have been persistently stimulated by TNFα + IL-1β." (PMID 34072893, 2021). "In this step, IL1-β expressed by resident activated immune cells promotes CAF induction via NF-κB signalling, thereby resulting in a proangiogenic and tumor-promoting inflammatory response as a result of the recruitment of macrophages into the tumor." (PMID 34771577, 2021). "This revealed that primary tumor-stimulated lung but not liver contained nonvesicular full-length IL1β-mRNA." (PMID 34135341, 2021). "Our findings are in accordance with the previous statements, as we found that both ADMSC and mature adipocytes secrete factors that could contribute to tumor development like IL6, EGF, PTGS2 and IL4 in ADMSC, and CCL5, IL1β and IGF in adipocytes." (PMID 33801973, 2021).
tumor (continued). "Mice treated with C-87 exhibited lower concentrations of the following pro-inflammatory cytokines in the tumor paw compared to vehicle-treated tumor-bearing mice: TNFα (p < 0.05), NGF (P < 0.05), IL1β (P < 0.05), IL4 (P < 0.05), IL28β (P < 0.001), IL33 (P < 0.01), MIP3α (P < 0.01)." (PMID 33469141, 2021). "Il-1β-deficient mice failed to infiltrate inflammatory monocytes, but CD11b+ dendritic cells and activated CD8+ T cells were more predominant in tumor tissues compared to wild type (WT) mice." (PMID 33686176, 2021). "In summary (graphical abstract), we reveal that SPTBN1 functions as a tumor suppressor to stabilize SOCS1 protein, controlling the cellular level of p65 to suppress the expression of inflammatory cytokines, IL-1α, IL-1β and IL-6, and the expansion of MDSCs and Foxp3+Treg cells." (PMID 33754058, 2021). "IL-1α and IL-1β are both constitutively expressed in OSCC, can be found in the saliva of patients with OSCC, and have been reported to have important functions in OSCC carcinogenesis and tumor progression." (PMID 35047997, 2021). "Moreover, in B16 tumor-bearing Fats−/− mice, serum levels of proinflammatory cytokines (IFN-γ, IL-12, and IL-1β) were increased, while the level of the anti-inflammatory cytokine IL-10 was significantly decreased." (PMID 34262035, 2021). "Chronic inflammation is the key driver of the CAC; the RNA-seq transcriptome study demonstrated that MSCs reduce tumor initiation through immune responses, so we detected pro-inflammatory cytokines TNF-α, IL-1β, and IL-6 in serum to determine the systematic immune responses." (PMID 34150751, 2021). "Here we proposed that a 2-gene signature of IL-1β (M1) and TGF-β1 (M2) could represent the features of MPE-Mφ and tumor tissues (TCGA dataset) to indicate their significance in the OS of late-stage NSCLC patients." (PMID 33175182, 2021). "However, IL-1β secreted by M1 macrophages can increase the expression of PD-L1 in HCC cells, promote tumor progression, and affect the prognosis of tumor patients." (PMID 35059434, 2021). "We found that IL-1B regulates iNOS+ immune cell infiltration, without affecting either the accumulation of CD163+ immune cells or the growth of tumour-associated CD34+ blood vessels." (PMID 34290237, 2021). "These included IL-12p70, pro-inflammatory IL-1β, and TNF, as well as MIP-3α (CCL20) and MIP-3β (CCL19), which are chemotactic for lymphocytes and DCs, and IFN-α, which is known to activate antigen presentation for T cell-mediated tumor cell recognition." (PMID 34912334, 2021). "IL-8, IL-1β, MCP-1, RANTES, TNFα, and IL-6 also promote tumor cell migration and invasion." (PMID 34067089, 2021). "Likewise, EA reduced the expressions of IL-1β protein and TNF-α protein and increased the expression of IL-10 protein in tumor tissues." (PMID 35095910, 2021). "Moreover, studies have shown that among tumor-infiltrating immune cells, macrophages promote lymphangiogenesis via NLRP3-dependent IL-1β secretion." (PMID 34737710, 2021). "Furthermore, it was found that the LLC tumor group showed high levels of TNF-α, IL-1β, and IL-6, and Alp reduced their serum concentrations in a dose-dependent manner." (PMID 34093209, 2021). "Similarly, M-MDSCs are recruited to the lungs by tumor-secreted CCL12 and drive tumor cell adhesion to the vascular endothelium through secretion of IL-1β." (PMID 34830776, 2021). "Some M1 markers (IL1A, IL1B, CD86), M2 markers (CCL18, MRC1/CD206, CSF1R), and TAM markers (HLA-DR, IL1RN, CD163, ITGAM, SIGLEC1/CD169) were highly expressed on both tumor and non-tumor macrophages." (PMID 33918618, 2021). "Immunofluorescence microscopy showed that IL-1β was present in the cytoplasm of both tumour and non-tumour cells all cells treated with either Smp24 or Smp43." (PMID 35082671, 2021). "Thereafter, IL-1β phosphorylates glycolytic enzyme glycerol-3-phosphate dehydrogenase (GPD2) and activates the phosphatidylinositol-3-kinase (PI3K) pathway, thus supporting tumor cell survival and growth." (PMID 34439380, 2021).
tumor (continued). "To elucidate whether PD-H administration led to a change in the level of IL-1β expressing immune cells in the TME, we performed flow cytometry analysis from harvested tumor samples." (PMID 34696348, 2021). "In addition, pyroptosis activation in tumor cells by CAR-T cells leads to the release of DAMPs, such as HMGB1, that also trigger macrophages to release IL1β and IL6." (PMID 34685542, 2021). "Moreover, it is known that the inflammation and associated with an upregulation of proinflammatory mediators such as IL-1β, IL-6, IL-8, and TNF-α, and prostaglandins by leukocytes play a major role in tumor development in TME." (PMID 34660256, 2021). "Taken together, these data suggest that rIL-1RA could be a beneficial alternative for the inhibition of tumor-dependent angiogenesis, probably by reducing the production of VEGF, CXCL8, endothelin-1, IL-1β and hepatocyte growth factor (HGF)." (PMID 35048046, 2021). "Moreover, several pro-inflammatory cytokines, including TNF-α, IL-1β, IL-6 and IL-17, and induced cell apoptosis are decreased with anti-TNF-α treatment in HCC tumor cells." (PMID 34948424, 2021). "IL-6, IL-1β, and TNF-α are 3 cytokines relevant to immunosuppression and tumor progression." (PMID 34422050, 2021). "We previously showed that pharmacological inhibition of IL-1B signalling using the IL-1Ra, Anakinra, did not affect the growth of the primary tumour, whereas treatment with an anti-IL-1B antibody, Canakinumab, increased proliferation." (PMID 34290237, 2021). "As described with the LLC tumor model, HEI3090 did not impact the levels of IL-1β in this in situ genetic tumor mouse model." (PMID 33510147, 2021). "Intriguingly, these tumor cells were indeed found to express not only GSDMD, but also the upstream NLRP3-inflammasome components, akin to myeloid cells, and to display spontaneous signs of inflammasome activation and IL-1β production." (PMID 34490126, 2021). "Adhesional factors on the BBB endothelium such as ICAM-1, VCAM-1, or ACKR1 may be upregulated by IL-1β or IFN-γ, which can be delivered via convection-enhanced delivery (CED) directly to the tumor site." (PMID 34771532, 2021). "Activation of pyroptosis by CAR-T cells when they face tumor cells leads to the release of factors that activate caspase 1 for GSDMD cleavage in macrophages, which results in massive amounts of cytokines, including IL6 and IL1β." (PMID 34685542, 2021). "In co-cultures of MM cells with activated platelets, elevated levels of IL-1β are observed, which arise from MM tumour cells and not from platelets themselves, which contain minimal amounts of IL-1β." (PMID 34445745, 2021). "Upon knock-down of NLRP3 in the tumor, IL-1β processing is arrested and, therefore mature IL-1β-induced IL-6/STAT3 axis is no longer being amplified." (PMID 34531850, 2021). "This signal facilitated tumor progression, which was attenuated when NLRP3 or IL‐1β was inhibited." (PMID 32508035, 2020). "M1 and M2 play opposite roles, while M1 plays anti-tumor effects, M2 phenotype has an immunosuppressive effect and secretes TGF-B, IL-6, IL-1B, EGF, and other cytokines to promote the growth, invasion, and expansion of gliomas by stimulating tumor-related blood vessel formation and tumor metastasis." (PMID 33511267, 2020). "IL-1β and IL-23 increased IL-22 production of ILC3 in the tumor tissue." (PMID 32649314, 2020). "We found a significant tumor-effect on increasing IL-1β levels in BAT although ghrelin did not prevent this increase, suggesting tissue-specific differences in inflammation between BAT and WAT in response to tumor and ghrelin." (PMID 32934774, 2020). "The cells exhibiting an active cell cycle progression were reduced in tumor tissues of AIMP1-treated mice, and the blood levels of TNF-α and IL-1β were increased, indicating that AIMP1 might play an anti-tumor role by inducing tumor inhibiting cytokines." (PMID 32709848, 2020).